CCR6 (C-C motif chemokine receptor 6)
Diseases named in the same sentence as CCR6 in open-access papers (continued):
Sharing a sentence is not in itself a finding about the gene and the disease.
tumor (continued). "Th17 cells express CCR4 and CCR6, which are considered to be involved in their recruitment into the tumor microenvironment." (PMID 34885241, 2021). "On the other hand, an accumulating body of evidence indicates that the CCL20/CCR6 axis regulates endothelial behaviors related to tumor angiogenesis." (PMID 34774095, 2021). "CCL20 derived from tumor cells interacts with CD19CD5 B cells overexpressed by CCR6 to promote the development of HCC, possibly through enhanced angiogenesis." (PMID 34869376, 2021). "Local injection promoted activation of the CCL20/CCR6 pathway in the tumor microenvironment and further elevated the expression of several molecules related to lymphocyte activation." (PMID 34966384, 2021). "The recruitment of CD31+ vessels into Matrigel plugs supplied with Ccl20 and injected into mice, which was abrogated when plugs were injected into a Ccr6-deficient mouse strain, further substantiates an angiogenic role for CCL20 in the tumour microenvironment." (PMID 32601464, 2020). "Published data revealed that miR-21 was highly expressed on CCR6+ Tregs and important for their dominant enrichment in tumor tissue, which was closely related to the poor prognosis of breast cancer patients." (PMID 32911844, 2020). "Studies have reported that the CCL20/CCR6 axis plays a key role in the tumor-chemokine network and promotes tumor progression in HCC and CRC." (PMID 31991604, 2020). "Inhibition of miR-21 significantly reduced the proliferation of CCR6+ Tregs in vitro, altered the enrichment of CCR6+ Tregs in the tumor mass and exerted an effective antitumor effect on CD8+ T lymphocytes." (PMID 32911844, 2020). "We characterize the phenotype of EpCAM+ CD4+ T cells as PD-L1+ CCR5+ CCR6+ and further confirm that this subset also increases in tumor microenvironments with irregulated p38 MAPK signaling pathway." (PMID 31354723, 2019). "This study highlights hypoxia-induced tumor immunosuppression by TREM-1+ TAMs that attracts CCR6 + Foxp3 + Tregs, and TREM-1+ TAMs confers HCC resistance to Programmed cell death 1 ligand 1 (PD-L1) treatment." (PMID 31464625, 2019). "CCR6 is expressed on a variety of immune cells including macrophages, dendritic cells and T-cells as well as on different tumor cells." (PMID 31561620, 2019). "M2-like macrophages produce CCL-20, which recruits CCR6-expressing B cells and γδ T cells, perhaps to the tumor environment." (PMID 31379820, 2019). "In a mouse model of breast cancer, it was also shown that CCL21 recruits CCR7-expressing ILC3s with an LTi phenotype (CD4+CCR6+) to the tumor environment." (PMID 31507605, 2019). "As our data indicate, TAMs likely secrete CCL20, and CCR6-expressed RCC cells consume CCL20 in the tumor microenvironment of RCC, resulting in an increased migration ability of the RCC cells." (PMID 31905918, 2019). "Th17 cells, mostly mediating potent antitumor immunity by recruiting CD8+ T cells, NK cells, and dendritic cells (DCs) into the tumor microenvironment, express high levels of CCR6 and CXCR4 and low levels of CCR7." (PMID 30591657, 2018). "Regarding the function of Tregs in the TME, miR-21 has been found to be highly expressed in CCR6+ Tregs in tumor tissues from a murine breast cancer model." (PMID 30443251, 2018). "Silencing of miR-21 altered the enrichment of CCR6+ Tregs in the tumor mass and enhanced the antitumor effect of CD8+ T cells." (PMID 30443251, 2018). "CCR6 and CCR10 are implicated in Treg homing to tumors, and were more highly expressed by the CD39+ Treg in the tumor." (PMID 30651930, 2018). "In a tumor microenvironment, Th9 cells were found to produce CCL20, which facilitate the migration of CCR6+ leukocytes in the tumor tissue." (PMID 29867972, 2018). "TH9 cells also induce host anti-tumor CD8+CTL responses by upregulating the CCL20/CCR6-dependent recruitment of dendritic cells (DCs) to local tumor tissues." (PMID 27589682, 2016).
tumor (continued). "We found that MMTV-PyMT Ccr6−/− mice had significantly decreased tumor incidence compared to MMTV-PyMT Ccr6WT animals." (PMID 26047945, 2015). "This, combined with the decreased tumor growth in the CCR6-null mice, indicated that the support of macrophages is essential at the early stages of tumor growth." (PMID 26047945, 2015). "Tumor cells produce chemokines, such as MIP-3α, which recruit immature DCs via CCR6; and after capturing tumor antigens, DCs migrate to secondary lymphoid tissues to initiate T cell responses against the tumor." (PMID 26690204, 2015). "Our results showed that Th17 cells highly aggregated within tumor tissues in an activated phenotype with markedly increased expression of CCR6." (PMID 25768730, 2015). "The deletion of CCR6 also resulted in reduced trafficking of dendritic cells to the tumor site, consistent with previous studies, which demonstrated a reduced overall migratory ability of dendritic cells in CCR6-null mice." (PMID 26047945, 2015). "Deletion of CCR6 delayed tumor onset, significantly reduced the extent of initial hyperplastic outgrowth, and decreased tumor incidence in PyMT transgenic mice." (PMID 26047945, 2015). "Our findings thus suggest that CCR6 promotes mammary tumorigenesis through an epithelium-independent mechanism involving tumor-infiltrating macrophages." (PMID 26047945, 2015). "CCR6 was then shown to promote the recruitment of pro-tumorigenic macrophages to the tumor site, facilitating the onset of neoplasia." (PMID 26047945, 2015). "CCR6/CCL20 in tumor microenvironments in addition plays a crucial role in driving phenotypic switch of hematopoietic cells with increased potential for angiogenic EC differentiation and attenuated proinflammatory activity." (PMID 25110692, 2014). "Ccr6 was found to be expressed at a higher level in tumor tissue as compared to adjacent uninvolved normal tissue." (PMID 24866282, 2014). "Herein we demonstrate that CCR6 plays a critical role in CRC cell aggressiveness both in vitro and in vivo settings, indicating that CCR6 on tumor cells is functional." (PMID 24979261, 2014). "Ten days after tumor cell inoculation, the grafted CCR6−/− mice were randomly divided into two groups for treatment, IgG control or anti-CCR6." (PMID 24979261, 2014). "Relative expression of Ccr6 normalized to the house-keeping gene β-actin was compared between normal and tumor tissue." (PMID 24866282, 2014). "In a mouse CRC model, CCR6(+) Tregs are recruited into the tumor by responding to CCL20 secreted not only by tumor cells but also by TAMs." (PMID 25110692, 2014). "Similar to CMT 93, murine CT26 cells displayed low CCR6 expression before grafting to hosts, however CCR6 was strongly expressed in the tumor tissues 10 days post injection." (PMID 24979261, 2014). "Tregs in peripheral blood of HCC patients preferentially up-regulate CCR6, which facilitates their migration to tumor sites." (PMID 25000974, 2014). "In this study, we demonstrated that targeting the CCR6 in the tumor cell or the tumor microenvironment inhibited CRC progression in mice." (PMID 24979261, 2014). "CC chemokine receptor 6 (CCR6) axis has an important role in recruiting Tregs to tumor sites in HCC; TGF-beta and macrophage-derived chemokine (CCL22) signaling pathways induce aggregation of Tregs at the tumor sites in HCC too." (PMID 25000974, 2014). "In other situations of inflammation or tumor, CXCR3, ChemR23, and CCR6 are implicated to be involved in pDCs migration to periphery tissues." (PMID 24734242, 2014). "The aberrant expression of the chemokine receptor CCR6 on CRC cells is reportedly involved in organ-selective tumor metastasis." (PMID 24979261, 2014). "Another relatively uninvestigated factor that promotes the recruitment of CCR6+ regulatory DCs to tumor locations is the expression of β-Defensins by epithelial cells and inflammatory leukocytes." (PMID 24339824, 2013).
tumor (continued). "Second, the Tcregs in PBMCs showed high levels of expression of CCR6, a ligand of chemokine CCL20, which is usually overexpressed in the NPC tumor microenvironment and upregulated by the EBV-encoded LMP1 protein." (PMID 22051182, 2011). "Combining these data suggested that compared to CCR6−Tregs, local prior proliferation of CCR6+ Tregs was critical for their dominant accumulation in tumor mass." (PMID 21655250, 2011). "Tumor-infiltrating Th17 cells express high levels of CCR4 and CCR6 and therefore respond to tumor-derived CCL20 signals." (PMID 21197451, 2011). "Tumor resident DCs were found to trigger the proliferation of CCR6+Tregs in a TGF-β dependent manner." (PMID 21655250, 2011). "Others and we have shown that CCL20/CCR6 auto-signaling occurs in prostatic cancerous cells and that tumor CCR6 expression correlates with disease aggressiveness, thus marking intra-tumoral CCL20/CCR6 interactions as a pro-carcinogenic axis." (PMID 21949768, 2011). "It was found that 52.6% CCR6+Tregs were BrdU-positive, significantly higher than 13.4% BrdU-positive- CCR6−Tregs (p<0.05) in tumor mass." (PMID 21655250, 2011). "In order to expand the sampled data, we performed an additional analysis of CCR6 expression using a tumor tissue array enclosing over 50 lung-adenocarcinoma samples homogenously spread among the different disease stages." (PMID 21949768, 2011). "Here, we further found that tumor-resident DCs significantly triggered the proliferation of CCR6+T cells in a TGF-β dependent manner." (PMID 21655250, 2011). "Here we show that intra-tumoral levels of CCL20 were elevated as compared to tumor adjacent lung tissue and that CCR6 positive immune cell infiltrates were found in the tumor parenchyma." (PMID 21949768, 2011). "Our results suggest that CCR6 expression on tumor cells and that infiltration by CCL19-expressing DC contributes to breast cancer dissemination." (PMID 21624121, 2011). "5a, vinblastine pre-treatment obviously decreased CCR6+Treg frequency in tumor mass from 5.43% to 2.13% (p<0.05)." (PMID 21655250, 2011). "Tumor-resident CD11c+ DCs, macrophages or B cells were isolated from tumor mass of 4T1 bearing mice and then cultured with CCR6+Tregs or CCR6−Tregs at 2∶1 ratio in vitro." (PMID 21655250, 2011). "The expansion of CCR6+Tregs and their CCR6− counterpart in tumor mass were determined by BrdU incorporation assay." (PMID 21655250, 2011). "CCR6+, CD1a+ and Langerin+ tumor-infiltrating DC were occasionally identified in serial tissue sections from the same tumor (not shown)." (PMID 21624121, 2011). "TAMs recruit CCR6+ Treg-cells to tumor mass and promote its development via enhancing the production of CCL20 in a CRC mouse model." (PMID 21559338, 2011). "Especially, we found that CCR6 is a liver-specific determinant for the trafficking of circulating Tregs into tumor." (PMID 21935436, 2011). "The effect and its possible mechanism of tumor-resident antigen presenting cells (APCs) on the proliferation of CCR6+Tregs also were evaluated." (PMID 21655250, 2011). "TAMs contributed to the increased CCL20 production in the tumor environment and recruited Treg-cells that expressed high levels of CCR6." (PMID 21559338, 2011). "Here, we further provided direct evidence showed that prior proliferation of CCR6+ Tregs was critical for their local enrichment and subsequently contributed to their suppressive effect on anti-tumor CD8+T cells in vivo." (PMID 21655250, 2011). "Further study demonstrated that tumor-resident DCs triggered the proliferation of CCR6+Treg cells in TGF-β dependent manner." (PMID 21655250, 2011). "It is seemingly recuitment of CCR6+Tregs didn't be mostly responsible for their dominate enrichment in tumor sites." (PMID 21655250, 2011). "Our recent work indicated that adoptive transfer of CCR6+Tregs more effectively suppressed the anti-tumor CD8+T cells than their CCR6− counterparts did." (PMID 21655250, 2011).
tumor (continued). "The administration of recombinant mouse CCL20 resulted in a marked accumulation of CCR6+ Treg-cells in tumor sites as detected by both immunofluorescence staining and an in vivo fluorescence imaging." (PMID 21559338, 2011). "CCR6 was detectable in tumor cells, while CCL19 was expressed by both tumor cells and stroma-infiltrating cells exhibiting a dendritic morphology." (PMID 21624121, 2011). "And it was found that predominant in situ proliferation of CCR6+Tregs was critical for their local enrichment and subsequently their suppression in tumor immunity." (PMID 21655250, 2011). "Together, these data indicate that TAMs support the accumulation of CCR6+ tumor-infiltrating Treg-cells, and, at least in part via this mechanism, promote the release of CCL20 in CRC in mice." (PMID 21559338, 2011). "Two weeks after CMT93 grafting, tumor-infiltrating Treg-cells in CCR6 −/− mice were examined by Flow cytomery." (PMID 21559338, 2011). "Our data showed that CCR6+Tregs were dominantly enriched in the tumor mass during tumor progression." (PMID 21655250, 2011). "Previous studies evaluating CCR6 expression levels by immunohistology in 64 CRC primary tumor specimens found that CCR6 staining was significantly stronger in cancer cells compared with adjacent colon epithelial cells." (PMID 21559338, 2011). "We further showed that Th17 cells can be induced and expanded in tumour microenvironment through cytokines produced by tumour cells and TILs, and in addition can be recruited to the tumour milieu through a CCR6/CCL20-dependent mechanism." (PMID 20877351, 2010). "CCR6-positive cells showing dendritic morphology were randomly distributed throughout the tumour bed in all cases investigated." (PMID 20969772, 2010). "Our recent results provide a novel mechanism for CXCR4-mediated tumor growth and metastasis and establish a functional link between CXCR4/CXCL12 and CCR6/CCL20 pathways in tumor development." (PMID 19340288, 2009). "Experiments performed with CCR6-immunotoxins suggest that the role of VLCs to tumour vasculogenesis takes place primarily during the early stages of tumour growth." (PMID 15785750, 2005). "CCR6 represents a tumor-intrinsic invasion axis in advanced CTCL." (PMID 41614909, 2026). "The increased fatty acid uptake by tumor cells can recruit more CCR6+ Tregs." (PMID 41176774, 2025). "The Hh‐CCL20‐CCR6 axis may also influence other CCR6‐positive immune subsets and tumour cell‐intrinsic processes, including metastasis and angiogenesis." (PMID 40913253, 2025). "This establishes the association between the Hh pathway and the CCL20/CCR6 axis in HCC progression, highlighting a mechanism by which Hh pathway activation may drive tumour‐promoting inflammation in HCC." (PMID 40913253, 2025). "qPCR data revealed that the HER2-CXCR5-CCR6-CAR T cells displayed the highest copy number of HER2 cells in the tumor tissue, with the groups expressing either CXCR5 or CCR6 alone showing intermediate levels, both significantly exceeding those of the HER2-CAR T and Control-T group." (PMID 40764989, 2025). "Notably, CCR6+ Treg cells were enriched in tumor-infiltrating lymphocytes (TILs) and metastatic lymph nodes compared to peripheral blood mononuclear cells (PBMC)." (PMID 41445742, 2025). "CCR6 expression is deregulated in some human malignancies and may be involved in the tumor progression." (PMID 38169378, 2024). "In colorectal cancer, CCR6 enhances tumour angiogenesis via the AKT/NF-κB/VEGF cell signalling." (PMID 38493218, 2024). "Furthermore, CCR6 staining was significantly stronger in tumour tissues and was positively correlated with CD31 staining." (PMID 38493218, 2024). "Therefore, HOXD3 can facilitate HCC metastasis by upregulating CCR6 expression, and CCR6 co-ordinates the tumour progression by playing the multiple functions on HCC and ECs." (PMID 38493218, 2024). "CCR6 was delivered by exosomes to endothelial cells and promoted tumour migration." (PMID 38493218, 2024).
tumor (continued). "In addition, TREM-1 + TAMs also respond to hypoxic conditions and tumor metabolites through the ERK/NF-κβ pathway, resulting in an increase in CCR6 + Foxp3 + Tregs, which promotes tumor immunosuppression and creates resistance to PD-L1-targeted therapies." (PMID 39068459, 2024). "There is evidence that blocking CCR6 activity in the tumor microenvironment inhibits tumor neovascularization and, therefore, might enhance traditional therapy’s effectiveness." (PMID 38473265, 2024). "Furthermore, CCR6 expressed on the surface of Tregs as a CCL20 receptor has been investigated in tumor immunity." (PMID 38902257, 2024). "An additional reason for decreased functionality of multiple-transduced cells may be a synergistic PD-1 induction dependent on different chemokine receptors: CCR6 showed increased PD-1 expression in the tumor and CCR4 in draining lymph nodes." (PMID 37301772, 2023). "CCR6 might affect tumor immunology, which was the possible immunotherapeutic target but not merely the prognostic marker." (PMID 37182147, 2023). "Furthermore, intra-tumoral Tc17 cells also express CCL20, CCR4, CCR6, and CXCR6 which have previously been associated with tumor progression in HCC patients." (PMID 38567057, 2023). "Lastly, because CCR4 and CCR6 both conferred increased therapeutic efficacies, we tested whether co-transduction of these two chemokine receptors improves anti-tumor efficacy." (PMID 37301772, 2023). "Furthermore, Th17 cells were found to be responsible for CCL5 and CCL20 secretion, which are known to recruit CD8+ T cells (CCR5+ CCR6-) in the intraepithelial regions of the tumor." (PMID 37185750, 2023). "In accordance with our results, as a result, CCR6 level may only be related to late tumor stage (III to IV) and OS rate." (PMID 37182147, 2023). "Additionally, treatment of HBAAV‐TBG‐shALKBH5 or/and CCR6 inhibitor markedly decreased tumour volume and liver/body weight ratio, promoted tumour necrosis and inhibited ALKBH5/TIRAP axis in tumour." (PMID 36792369, 2023). "Indeed, DC precursors, recruited to tumor sites via the β-defensin-CCR6 axis, can be transformed into endothelial-like cells with tumor-promoting functions when exposed to VEGF." (PMID 36949244, 2023). "Additionally, we observed a positive correlation between the CCR6 mRNA expression level in tumor tissue of smokers and smoking history (amount of PYs)." (PMID 37316552, 2023). "A statistically significant difference was observed in the expression level of CCR6 mRNA between tumor tissue of SCC patients and control tissue (p = 0.044, Mann–Whitney U-test), with a lower CCR6 mRNA expression level in tumor tissue (median RQ: 7.781 and 17.498, respectively)." (PMID 37316552, 2023). "In addition, a significant positive correlation was observed between the expression level of CCR6 and linc00673 in tumor tissue (p = 0.01, rho = 0.466, Spearman’s rank correlation)." (PMID 37316552, 2023). "Furthermore, the tumor-promoting effects of CCR6/CCL20 within the tumor microenvironment have been reported in many cancer types, such as renal cell carcinoma, gastric cancer, cervical cancer, and lung cancer." (PMID 37218898, 2023). "Targeting CCR6 on tumor cells may be a potential strategy for inhibiting CRC metastasis by enhancing the efficacy of immune checkpoint inhibitors, but further research is needed to fully understand the role of CCR6 in CRC and its metastasis." (PMID 37370832, 2023). "Less common immunosuppressive cell types in human HCC consist of B cell population expressing PD-1, Th17 cells, CD4+ T cells expressing CCR4 and CCR6, CD14+ DCs expressing CTLA-4 and PD-1, tumor-associated neutrophils, tumor-associated fibroblasts, and type-II T helper cells (Th2)." (PMID 36845131, 2023). "Similar to these studies, CAR-T cells overexpressing CCR6, the receptor of MIP3α, might be effective in poorly responsive patients with high baseline serum MIP3α levels in tumor tissues." (PMID 36869895, 2023).